KCNMA1 (potassium calcium-activated channel subfamily M alpha 1)
Diseases named in the same sentence as KCNMA1 in open-access papers (continued):
Sharing a sentence is not in itself a finding about the gene and the disease.
melanoma (13 papers, 2010 to 2025). A malignant, usually aggressive tumor composed of atypical, neoplastic melanocytes. "Among the ion channels expressed in melanoma, the large-conductance K+ channel—also known as the BK channel, and encoded by the KCNMA1 gene—plays a complex and ambiguous role in human cancer." (PMID 34445066, 2021). "Another alternative possibility is that miR-211 down-regulation in melanoma causes other transformational events unrelated to KCNMA1, leading to higher oncogenesis and invasiveness." (PMID 21072171, 2010). "We demonstrate that the increased expression of one particular confirmed target transcript, KCNMA1, is associated with high invasiveness and proliferation in melanoma cells in vitro." (PMID 21072171, 2010). "The simplest model we offer is that the down-regulation of miR-211 causes elevated levels of KCNMA1 protein in melanoma cells, which at least in part explains the invasiveness of malignant melanoma." (PMID 21072171, 2010). "In melanoma, BKCa encoding gene KCNMA1 was found to be the target of miRNA-211." (PMID 27233075, 2016). "The expression of KCNMA1, encoding a calcium ion-regulated potassium channel protein, appears to at least partially account for the high cell proliferation rate and invasiveness of melanoma cell lines." (PMID 21072171, 2010). "Since the over-expression of KCNMA1 is often associated with both cell proliferation and cell migration/invasion in various cancers, we decided to determine whether the depletion of miR-211 and associated over-expression of KCNMA1 were important for these processes in melanoma cells." (PMID 21072171, 2010). "KCNMA1 protein expression was very low in normal melanocytes, but high in all melanoma cell lines, indicating an inverse correlation of expression between KCNMA1 protein and miR-211." (PMID 21072171, 2010). "The recent finding that salinomycin, an inhibitor of K+ transport, is a selective inhibitor of cancer stem cell proliferation is consistent with our findings on the role of KCNMA1 in melanoma cells." (PMID 21072171, 2010). "The down-regulation of miR-211 and the corresponding up-regulation of its target transcript KCNMA1 are therefore important molecular events for melanoma development and/or progression." (PMID 21072171, 2010). "We report here the reduced expression of miR-211 in these cell lines and clinical isolates of human melanomas, and present evidence that a principal effect of the reduced expression of miR-211 is the increased expression of its target transcript KCNMA1." (PMID 21072171, 2010). "We next investigated whether the induced expression of miR-211 in melanoma cells can reduce KCNMA1 transcript levels." (PMID 21072171, 2010). "While the assays of cell invasion reported here are widely used for demonstrating metastatic potential, and the results appear convincing, further in situ studies with immunodeficient mice are needed to confirm the role of KCNMA1 in melanoma invasiveness in vivo." (PMID 21072171, 2010). "An shRNA against KCNMA1 mRNA also demonstrated similar effects on melanoma cells." (PMID 21072171, 2010). "On the other hand, several metastatic lines—including IGR37—regained significant expression of TRPM1 and showed reduced expression of KCNMA1, KCNN4, and TRPM2, compared to the primary melanoma lines (third row)." (PMID 34445066, 2021). "Another target of miR-211 is potassium calcium-activated channel subfamily M alpha 1 (KCNMA1), overexpressed in A375 melanoma stem-like cells due to the endogenous low levels of miR-211." (PMID 33348804, 2020). "If true, it raises the possibility that one of the ways MITF might also suppress melanoma metastasis is through its transcriptional activation of miR-211 via the TRPM1 promoter, and the consequent negative post-transcriptional effects of miR-211 on KCNMA1 mRNA." (PMID 21072171, 2010).
Obesity (13 papers, 2011 to 2025). Accumulation of substantial excess body fat. "The results from case–control cohorts involving 4,838 obese and 5,827 control subjects suggested that the KCNMA1 rs2116830*G variant was associated with obesity with a p value of 2.82×10−10." (PMID 34744789, 2021). "Results from a few studies have shown a strong association between KCNMA1 splicing variants and the incidence of obesity or DM." (PMID 34744789, 2021). "In humans, variants located in KCNMA1 have consistently been associated with obesity, and CTNNA2 has been associated with plasma levels of vitamin K, that plays a crucial role in heart diseases and with cardiovascular measures of the autonomic tone." (PMID 32599723, 2020). "We have identified KCNMA1 as a new susceptibility locus for obesity, and confirmed the association of the BDNF locus at the genome-wide significant level." (PMID 21708048, 2011). "For the new obesity susceptibility locus rs2116830 (KCNMA1) we performed quantitative trait analysis of BMI in three adult population-based samples, n = 4133 in total." (PMID 21708048, 2011). "The two susceptibility loci for obesity reported here, KCNMA1 and BDNF displayed nominal allelic association with obesity in each investigated adult case-control cohort." (PMID 21708048, 2011). "We therefore cannot exclude a change of KCNMA1 expression y in other organs in association with obesity." (PMID 21708048, 2011). "We have identified one new susceptibility locus for obesity near KCNMA1 (rs2116830) and confirmed association with BDNF (rs988712), by GWA analysis in a limited sample of morbidly obese and lean adults This study was followed up by genotyping of five additional European case-control cohorts." (PMID 21708048, 2011). "In conclusion, we identified KCNMA1 as a novel susceptibility locus for obesity, which may promote obesity at least in part by acting in adipose tissue." (PMID 21708048, 2011). "Potassium channel, calcium activated, large conductance, subfamily M, alpha member (KCNMA1) rs2116830*G and BDNF rs988712*G were associated with obesity in five of six investigated case-control cohorts." (PMID 21708048, 2011). "To elucidate potential mechanisms of action of KCNMA1 rs2116830 in obesity we determined mRNA levels of in human abdominal subcutaneous adipose tissue from obese and lean subjects." (PMID 21708048, 2011). "It is tempting to speculate that KCNMA1 is of minor importance for the development of a moderate increase in fat mass, but contribute to excessive accumulation of adipose tissue in obesity." (PMID 21708048, 2011). "We did not have access to tissue samples to study KCNMA1 expression in other organs, including the organ strongest implicated in regulation of food intake and obesity, the brain." (PMID 21708048, 2011). "Adipose tissue (P = 0.0001) and fat cell (P = 0.04) expression of KCNMA1 was increased in obesity." (PMID 21708048, 2011). "In order to further evaluate mechanisms by which KCNMA1 could contribute to the pathogenesis of obesity we performed gene expression studies in adipose tissue and observed increased KCNMA1 mRNA expression in obesity." (PMID 21708048, 2011). "This suggests the possibility that KCNMA1 is purely associated with obesity rather than BMI, but given the relatively small numbers of controls, this result might simply reflect a lack of statistical power." (PMID 30121879, 2018). "This may also be true for the novel obesity gene KCNMA1 identified in this study." (PMID 21708048, 2011). "Thus, KCNMA1 could hypothetically contribute to obesity by increasing number of fat cells." (PMID 21708048, 2011). "Thus, impaired expression of Kcnma1 and Kcnmb1 in the DSM contributes to obesity-induced OAB, suggesting that BK channels could be a useful treatment targets in OAB." (PMID 31480021, 2019).
Obesity (continued). "However, the associations of KCNMA1 and BDNF with childhood obesity are less evident and need to be comfirmed in additional cohorts; with both genes being associated with obesity in French but not in German children." (PMID 21708048, 2011).
generalized epilepsy (12 papers, 2013 to 2021). Epilepsy that is characterized by generalized seizure types and may have typical interictal and/or ictal EEG findings that accompany generalized seizure types (for example generalized spike-wave). "Mutations in KCNMA1 increase Ca2+ sensitivity of the channel by three- to five-fold, resulting in generalized epilepsy and paroxysmal dyskinesia." (PMID 33333793, 2020). "A missense mutation in KCNMA1 (p.Asp434Gly) was detected in a large family with generalized epilepsy and paroxysmal dyskinesia." (PMID 27064559, 2016). "In humans, the KCNMA1 gain-of-function mutation D434G has been found in patients suffering from KCa1.1-channelepsy that is characterized by generalized epilepsy and paroxysmal dyskinesia." (PMID 25784856, 2015). "– KCNMA1 gain-of-function mutations: cause generalized epilepsy and paroxysmal dyskinesia." (PMID 25784856, 2015). "With the development of generation gene sequencing technology, many KCNMA1 mutants have been identified and are more closely related to generalized epilepsy and paroxysmal dyskinesia." (PMID 35095492, 2021). "KCNMA1 (potassium channel, calcium-activated, large conductance, subfamily M, alpha member 1): KCNMA1 pathogenic variants were first reported in a family with AD generalized epilepsy and paroxysmal non-kinesigenic dyskinesia." (PMID 33919646, 2021). "Initially, the KCNMA1 mutations were illustrated in a large family with generalized epilepsy and paroxysmal nonkinesigenic dyskinesia." (PMID 29545233, 2018). "Heterozygous mutations in KCNMA1 were first illustrated in a large family with generalized epilepsy and paroxysmal nonkinesigenic dyskinesia." (PMID 29545233, 2018).
Intellectual disability (11 papers, 2018 to 2024). "Human KCNMA1 mutations are primarily linked with neurological conditions, such as seizures, developmental delay, movement disorders, and intellectual disability." (PMID 36677942, 2023). "We describe the case of a 25-year-old Caucasian male with autism spectrum disorder and severe intellectual disability presenting large-conductance calcium-activated potassium channel haploinsufficiency due to a de novo balanced translocation (46, XY, t [q23;q22]) disrupting the KCNMA1 gene." (PMID 35509069, 2022).
ischemia (10 papers, 2010 to 2025). A hypoperfusion of the BLOOD through an organ or tissue caused by a PATHOLOGIC CONSTRICTION or obstruction of its BLOOD VESSELS, or an absence of BLOOD CIRCULATION. "The KCNMA1 subunit is part of a large-conductance potassium channel that affects neuronal excitability and has been implicated in opioid analgesia, neuropathic pain, and kappa opioid receptor-mediated cardiomyocyte response to ischemia." (PMID 35625888, 2022). "We further tested the role of EVs derived from Kcnma1+/+ mice in protecting the heart from ischemia-reperfusion injury." (PMID 39747826, 2025). "Indeed, it has been shown that BMS-204352, a BK channel isoform, non-selective (KCNMA1) opener, can be neuroprotective in several different experimental assays, including brain trauma, spinal cord injury, and ischemia." (PMID 37513884, 2023).
fragile X syndrome (9 papers, 2013 to 2024). A genetic syndrome caused by mutations in the FMR1 gene which is responsible for the expression of the fragile X mental retardation 1 protein. "In addition, decreased protein expression of KCNMA1 resulting in reduced BKCa channel activity has also been observed in fragile X syndrome (FXS)." (PMID 35509069, 2022).
paroxysmal non-kinesigenic dyskinesia (8 papers, 2018 to 2025). "A similar phenomenon has also been seen for the potassium channel BK (KCNMA1) where mutations of the channel lead to paroxysmal non-kinesigenic dyskinesia (PNKD3) with a broad spectrum of developmental and neurological phenotypes and seizures seen in a proportion of the patients." (PMID 36618935, 2022).
paroxysmal dyskinesia (7 papers, 2015 to 2025). Paroxysmal dyskinesia (PD) is a rare heterogenous group of movement disorders manifesting as abnormal involuntary movements that recur episodically and last only a brief time. "The KCNMA1 variant was considered pathogenic for paroxysmal dyskinesia diagnosis (PNKD3; OMIM # 609446), an autosomal dominant disorder characterized by atonic falls or nodding and occasionally abnormal eye movements beginning in early childhood." (PMID 40785052, 2025).
Alzheimer disease (6 papers, 2015 to 2025). A progressive, neurodegenerative disease characterized by loss of function and death of nerve cells in several areas of the brain leading to loss of cognitive function such as memory and language. "We further focused on predicting key genes in neuroscience studies, including 4 genes with differential spatial and cellular expression (Kcnma1, Plp1, Ptgds, and Ttr), as well as the Alzheimer’s disease-related gene Apoe." (PMID 41210658, 2025). "Two independent genome-wide association studies reported that single nucleotide polymorphisms in the KCNMA1 gene encoding the BKα subunit and in the KCNMAB2 gene (regulatory subunit BKβ2) are strongly linked to the pathophysiology of Alzheimer’s disease (AD)." (PMID 30104956, 2018).
Dyskinesia (6 papers, 2018 to 2025). A movement disorder which consists of effects including diminished voluntary movements and the presence of involuntary movements. "N999S propagated the largest symptomatic burden with chemoconvulsant challenge and stress-triggered dyskinesia, supporting the conclusion that this variant has the greatest monogenic pathogenicity, followed by D434G, Kcnma1‒/‒, and H444Q." (PMID 35819138, 2022). "In transgenic mice engineered to carry the KCNMA1 GOF mutation D434G, differences were observed between homozygous and heterozygous mutant genotypes in neuronal firing patterns, seizure thresholds, and dyskinesia phenotypes." (PMID 40785052, 2025). "Treatment produced dramatic reductions in debilitating dyskinesia episodes, without provocation or exacerbation of other KCNMA1‐associated symptoms such as seizures." (PMID 35141357, 2022).
colorectal cancer (5 papers, 2014 to 2024). A primary or metastatic malignant neoplasm that affects the colon or rectum. "The primary aim of this study was to define the modulation of the KCNMA1 gene, both in a mouse model of colorectal cancer (CRC) and in human CRC samples." (PMID 30791468, 2019). "In the present study, we have evaluated the expression levels of KCNMA1 both in a mouse model of Colorectal Cancer (CRC) and in human CRC samples." (PMID 30791468, 2019). "It has been observed that in patients with colorectal cancer, levels of KCNMA1 are considerably low due to methylation, without being able to distinguish between cancer stages." (PMID 34638449, 2021).
endometrial cancer (5 papers, 2012 to 2023). Primary or metastatic malignant neoplasm involving the endometrium (mucous membrane that lines the endometrial cavity). "Amplification of KCNMA1 was restricted to a small but distinct fraction of breast, ovarian and endometrial cancer with the highest prevalence in invasive ductal breast cancers and serous carcinoma of ovary and endometrium (3–7%)." (PMID 22899999, 2012). "Our findings provide the first evidence that breast, ovarian and endometrial cancers carry also KCNMA1 amplification." (PMID 22899999, 2012). "Another K+ channel, the large-conductance voltage and Ca2+-activated K+ channel (KCa1.1, KCNMA1), is involved in cancer cell proliferation and migration, and it is aberrantly expressed in many types of tumors, including cervical, ovarian, and endometrial cancers." (PMID 37375748, 2023).
osteosarcoma (5 papers, 2009 to 2023). A usually aggressive malignant bone-forming mesenchymal neoplasm, predominantly affecting adolescents and young adults. "However, in osteosarcoma, KCNMA1 was shown to have antitumor property, suggesting that KCNMA1 may have diverse roles in different tumor types." (PMID 19640305, 2009).
ovarian carcinoma (5 papers, 2019 to 2024). A malignant neoplasm originating from the surface ovarian epithelium. "Gained-fused KCNMA1-CtBP2 gene may destroy the function of KCNMA1, which was overexpressed in ovarian cancer cells and promoted proliferation, migration and attenuation of apoptosis, and induced apoptosis in ovarian cancer cells." (PMID 34253710, 2021). "BKCa and calcium channels may be a suitable pharmacological target for treating recurrence and drug resistance in late-stage ovarian cancer patients who exhibit amplification of the KCNMA1 gene and calcium channel subunits genes (CACNA1D, CACNA1F, and CACNA1H)." (PMID 33923707, 2021). "In addition, oncogenic miR-1180, miR-493-5p, and miR-31 confer DDP resistance to ovarian cancer cells through silencing secreted frizzled-related protein 1(SFRP1), BRCA2, and potassium calcium-activated channel subfamily M alpha 1 (KCNMA1), respectively." (PMID 34512721, 2021).
Hypokalemia (4 papers, 2013 to 2023). An abnormally decreased potassium concentration in the blood. "Among the genes found to be repressed with malathion exposure in BMMCs, KCNMA1, which is associated with hypokalemia and paralysis, was detected." (PMID 37047231, 2023).
Liang-Wang syndrome (4 papers, 2021 to 2025). "Liang-Wang syndrome (LIWAS) is a polymalformative syndrome first described in 2019 caused by heterozygous mutation of the KCNMA1 gene encoding the Ca2+ and voltage-activated K+ channel (BKC)." (PMID 34563042, 2021). "Liang-Wang syndrome (LIWAS), a rare multi-malformation disorder caused by heterozygous mutations in the KCNMA1 gene encoding the large-conductance calcium-activated K+ channel (BKCa channel), was first reported in 2019." (PMID 40650956, 2025).
alcohol addiction (3 papers, 2013 to 2025). "Moreover, potassium channel genes, such as Kcnma1, which have been implicated in METH and alcohol addiction and genes, such as Eif2s1 and Ehd4, are implicated in drug abuse or reward circuits (Supplemental References)." (PMID 28751711, 2017).
brain tumors (3 papers, 2013 to 2016). "With this strategy, we seek to study the role of KCNMA1 in BTB permeability regulation in human brain tumor xenograft models." (PMID 23755013, 2013). "In addition, we are investigating the effect of KCNMA1 (codes for alpha subunit of BKCa channels) down-regulation on BTB permeability in human brain tumor model." (PMID 23755013, 2013).
breast tumor (3 papers, 2009 to 2018). "KCNMA1 expression was found to be higher in breast tumors and brain metastases." (PMID 20830292, 2010).
cervical cancer (3 papers, 2023 to 2025). A primary or metastatic malignant neoplasm involving the cervix. "In the case of KCNMA1 (KCa1.1), it has been proposed as an early marker for CCa since higher immunostaining of the protein is more prominent in high-grade dysplasia and cervical cancer tissues." (PMID 37375748, 2023). "No expression of this gene was detected in non-cancerous tissues, while more than half of LSIL (low-grade squamous intraepithelial lesion) samples showed its presence, and in HSIL (high-grade squamous intraepithelial lesion) and cervical cancer biopsies, KCNMA1 expression was found in all cases." (PMID 40361464, 2025).
clear cell renal cell carcinoma (3 papers, 2012 to 2017). "miR-149 expression has a direct correlation with KCNMA1 and LOX oncogenes in clear cell renal cell carcinoma." (PMID 23527086, 2013).